AMACR (alpha-methylacyl-CoA racemase)
Diseases named in the same sentence as AMACR in open-access papers (continued):
Sharing a sentence is not in itself a finding about the gene and the disease.
prostate carcinoma (continued). "Further, the increased expression of AR, KLK3 and AMACR in Patient 1 and 2 suggests the presence of prostate cancer cells within the mixed biopsy population." (PMID 30279484, 2018). "They reported positive expression of AMACR in all 137 prostate cancer specimens, and analysis revealed a sensitivity of 100 % and specificity of 88%." (PMID 30104809, 2018). "MPPA and MPP organoids expressed the clinical prostate cancer marker AMACR and developed prostate adenocarcinoma when grafted under the renal capsule in mice." (PMID 28881646, 2017). "Definition of a cancer type by setting a threshold of gene expression level is based on known data, generally from bulk-seq results, for example, PSA, PSMA, and AMACR for prostate cancer." (PMID 28881849, 2017). "The gene expression profile of the prostate cancer biomarker alpha-methylacyl-CoA racemase (AMACR) in these seven clinical samples was used as a positive control." (PMID 29203868, 2017). "Several other markers have been implicated as potential biomarkers of prostate cancer, such as alpha-methylacyl coenzyme A racemase (AMACR) which has been shown to be significantly up-regulated in prostate cancer and detectable in both serum and cancer tissue." (PMID 26237329, 2015). "Alpha-methylacyl-CoA racemase (AMACR) is routinely used as a biomarker in prostate cancer diagnosis as it is overexpressed in 80% of prostate cancers at the protein and mRNA level." (PMID 25514598, 2015). "On the other hand certain prostate cancer subtypes such as foamy gland carcinoma, atrophic and pseudohyperplastic carcinoma show low expression of AMACR." (PMID 25514598, 2015). "EO is a non-substrate-based covalent inactivator of AMACR and has selective toxicity to AMACR-expressing prostatic cancer cells in vitro." (PMID 25473890, 2014). "AMACR is indispensable in the catabolism of phytol-derived, branched-chain fatty acids and was first identified to be aberrantly overexpressed in prostatic carcinomas." (PMID 25473890, 2014). "RNA interference showed that high AMACR protein concentration promoted cell proliferation of prostate carcinomas through its enhanced enzymatic activity in an androgen-independent manner." (PMID 25473890, 2014). "AMACR is so consistently overexpressed in prostate tumors compared to benign tissue that it is used clinically as a marker to identify prostate cancer in ambiguous biopsies." (PMID 25132681, 2014). "AMACR was identified as being overexpressed in prostate carcinoma cells when compared with benign or normal prostate epithelial cells." (PMID 24130666, 2013). "AMACR protein overexpression was found in prostate cancers, low expression in any of the normal tissues or in benign prostatic tissue." (PMID 24130666, 2013). "AMACR (alpha-methylacyl-CoAracemase), an enzyme currently used in prostate cancer diagnosis, which is a peroxisomal and mitochon drial enzyme that was preferentially overexpressed to approximately 80% of prostate cancer detected in prostate biopsies." (PMID 24130666, 2013). "AMACR is abundantly expressed and is recognized as a standard tissue biomarker capable of a highly sensitive and specific diagnosis of prostate cancer." (PMID 24383053, 2013). "This study was designed to assess whether genetic variations of AMACR were associated with sporadic prostate cancer development in Korean men, known to be an ethnically homogenous population, by investigating the impact of AMACR polymorphisms on the risk of prostate cancer and clinical features." (PMID 24383053, 2013). "AMACR is a key enzyme in the ß-oxidation catabolic pathway of fatty acids and is known to be upregulated in several cancers including prostate cancer." (PMID 24383053, 2013). "A promising prostate cancer biomarker, alpha-methylacyl-CoA racemase (AMACR), has been previously demonstrated to distinguish cancer from healthy and benign prostate cells with high sensitivity and specificity." (PMID 25586028, 2012).
prostate carcinoma (continued). "AMACR has been consistently overexpressed in prostate cancer epithelium; hence it becomes an ideal specific biomarker for cancer cells within the prostate gland." (PMID 25586028, 2012). "Several molecules have been proposed as positive immunohistological markers of prostatic carcinoma, including α-methylacyl coenzyme A racemase (AMACR or P504S) and Prostate Tumour Overexpressed-1 (PTOV1)." (PMID 22800084, 2012). "We compared the usefulness for detecting prostate carcinoma of a three-marker cocktail of antibodies to α-methylacyl-CoA racemase (AMACR), p63 and cytokeratin (CK) 5 with a traditional two-marker cocktail of AMACR and p63." (PMID 22800084, 2012). "For this purpose, the well-known prostate cancer markers Hepsin and AMACR have been tested as positive controls." (PMID 21829708, 2011). "PCSD1 and LAPC4 also expressed AMACR, a biomarker that is often up-regulated in advanced prostate cancer." (PMID 22035283, 2011). "In category 2C, one case (initially reported as carcinoma) with crush artifact showed negativity for HMWCK and moderate positivity for AMACR hence confirming the diagnosis of prostate carcinoma." (PMID 21176184, 2010). "More recently a positive marker for prostate carcinoma, α-methylacyl CoA racemase (AMACR) has been reported to have sensitivity ranging from 82-100%." (PMID 21176184, 2010). "Although AMACR is a useful immunohistochemical marker for prostate cancer, it has significant limitations." (PMID 21176184, 2010). "But there are varied reports regarding the expression of AMACR in prostate cancer which ranges from 62% to 100%." (PMID 21176184, 2010). "The peptide-specific CTLs exerted significant cytotoxic activity against AMACR-expressing prostate cancer cells in the context of HLA-A24." (PMID 20003233, 2009). "AMACR is expressed abundantly in prostate cancer tissues as well as colorectal cancer and lung cancer tissues, whereas it is barely detected in benign tissues and normal prostate epithelial cells." (PMID 20003233, 2009). "We attempted to induce AMACR peptide-specific CTLs from PBMCs of HLA-A24 positive prostate cancer patients and assessed their cytotoxic activity." (PMID 20003233, 2009). "In the present study, we focused on AMACR, a novel antigen that is overexpressed in a variety of tumor tissues, including prostate cancer." (PMID 20003233, 2009). "In contrast, the AMACR mRNA level was elevated in all three prostate cancer cell lines (LNCaP, DU145 and PC-3) and in surgically resected prostate cancer tissues." (PMID 20003233, 2009). "We detected the overt expression of β-actin mRNA and AMACR mRNA in prostate cancer line LNCaP, but only very weak expression of AMACR mRNA was observed in normal adult liver and pancreas." (PMID 20003233, 2009). "High expression levels of AMACR have been described in various cancers, including prostate cancer, colorectal cancer and kidney cancer." (PMID 20003233, 2009). "Immunohistochemical analysis revealed that AMACR was present in prostate cancer tissues in 27 (69.2%) of the 39 patients." (PMID 20003233, 2009). "AMACR was identified as a tissue biomarker for prostate cancer by gene expression profiling of primary human prostate cancer and benign prostatic hyperplasia (BPH) using cDNA microarrays." (PMID 20003233, 2009). "In this study, the immunogenic potency of AMACR-derived peptides was assessed using PBMCs from prostate cancer patients." (PMID 20003233, 2009). "This idea is supported by recent findings that knockdown of AMACR transcripts or inhibition of the racemase activity effectively blocked growth of prostate cancer (PCa) cells." (PMID 19148275, 2009). "Alpha-methylacyl coenzyme A racemase (AMACR) was identified as one of the genes that were highly expressed in prostate cancer tissues through gene expression profiling using a DNA microarray and RT-PCR." (PMID 20003233, 2009). "In our study, AMACR was detected in about 70% of prostate cancer cases by immunohistochemical analysis." (PMID 20003233, 2009).
prostate carcinoma (continued). "RT-PCR and immunohistochemical analysis revealed that AMACR was strongly expressed in prostate cancer cell lines and tissues as compared with benign or normal prostate tissues." (PMID 20003233, 2009). "Immunohistochemical staining for AMACR is currently used in the clinical setting to support the histological diagnosis of prostate cancer." (PMID 20003233, 2009). "So far only AMACR/racemase has gained wider acceptance as a positive marker of prostate cancer, although is has two well-known limitations: intratumoral heterogeneity, which was confirmed in 45% of our cases, and AMACR-negative carcinomas." (PMID 18781151, 2008). "For example, alpha-methylacyl-CoA racemase, a phenotypic marker identified in the first microarray experiments on prostate cancer, was significantly over-expressed in malignant samples, but under-expressed in stem cells relative to committed cells." (PMID 18492237, 2008). "Alpha-methylacyl-CoA racemase, a phenotypic marker identified in the first microarray experiments on prostate cancer, was significantly over-expressed in cancer samples, as was MMP9." (PMID 18492237, 2008). "Immunohistochemically detected GOLPH2 protein expression was compared with the basal cell marker p63 and the prostate cancer marker α-methylacyl-CoA racemase (AMACR) in 614 radical prostatectomy specimens." (PMID 18781151, 2008). "Both AMACR and hepsin were upregulated in prostate cancer compared to benign prostatic epithelial cells." (PMID 17376245, 2007). "α-Methylacyl CoA racemase (AMACR) is a biomarker that was identified by both differential display and expression array analysis as a gene abundantly expressed in prostate cancer relative to benign prostate epithelium." (PMID 17125514, 2006). "α-Methylacyl-CoA racemase (AMACR) is a highly specific marker for prostate cancer." (PMID 39336516, 2024). "AMACR is a verified biomarker overexpressed in prostate cancer." (PMID 38566104, 2024). "To characterize the phenotypes of the epithelium in PCaT and normal prostate tissue and in derived early and late PCCs and PDOs, we assessed the expression of basal (CK5, p63) and luminal (CK18, AR1) epithelial markers and prostate cancer markers (AMACR and EZH2) by RT-PCR." (PMID 36769153, 2023). "AMACR is essential for lipid biosynthesis, which has an important role in fueling tumor progression, and expression knock-down and selective inhibition lead to reduced proliferation of several prostate cancer cell lines." (PMID 36611998, 2022). "Previous studies have shown that AMACR is upregulated in prostate cancer." (PMID 35627227, 2022). "Several studies also suggest that AMACR expression may be a marker of tumor differentiation in prostate cancer and breast cancer." (PMID 33755595, 2021). "Furthermore, they upregulate the expression of α-methylacyl-CoA racemase (AMACR), especially in prostate cancer tissue." (PMID 31436750, 2020). "Our study provides evidence that AMACR, a known prostate cancer marker, might also be a prognostic marker for GBM." (PMID 33154941, 2020). "Based on these results, it is estimated that AMACR expression and genetic variation may adversely affect prostate cancer." (PMID 32760737, 2020). "Moreover, 0.3 μM of PA or PRA in normal prostate cells was sufficient to increase the protein content of AMACR, an enzyme known to be elevated in prostate cancer tissue." (PMID 31436750, 2020). "Moreover, a reduction in AMACR expression by RNAi has been reported to reduce the growth rates of the prostate cancer cell line LAPC-4." (PMID 30219925, 2018). "However, there are relatively few studies on AMACR or AR mRNA expression levels in prostate cancer tissue." (PMID 26928323, 2016). "As an example of such a differential correlation, RNA levels of the prostate cancer biomarker gene AMACR have been found to have positive correlation with the tumor suppressor gene PTEN in adjacent normal tissue samples, but not in prostate cancer tissue samples." (PMID 27846853, 2016).
prostate carcinoma (continued). "All xenografts contained prostate cancer tissue confirmed by AMACR expression and loss of p63+ basal cells, and there was no obvious difference in pathology between groups." (PMID 27351281, 2016). "In contrast, in the human situation, TSPY was predominantly co-expressed with FOXA1 in the epithelial cells of PIN lesions and FOXA1 and another cancer biomarker, AMACR, in the adenocarcinoma cells in clinical prostate cancer samples of various degrees of malignancy." (PMID 24528896, 2014). "Besides the well known AMACR overexpression in prostate cancer, overexpression was also demonstrated in colorectal cancer." (PMID 24152881, 2013). "Almost all the prostate carcinomas were positive for AMACR and iNOS in varying intensity." (PMID 24353588, 2013). "Here, we found statistically significant association of AMACR polymorphisms with prostate cancer risk using single ethnic Koreans without any family history of immigration from other countries." (PMID 24383053, 2013). "Studies addressing the potential linkage between AMACR polymorphisms and sporadic prostate cancer risk in different populations, however, have not been consistent and have precluded any definitive conclusion." (PMID 24383053, 2013). "AMACR is essential for optimal growth of prostate carcinoma cells in vitro and this enzyme has the potential to be a complementary target with androgen ablation in prostate carcinoma treatment." (PMID 24353588, 2013). "We also found genetic variations of AMACR related to the histologic grade of prostate cancer." (PMID 24383053, 2013). "The synergistic effects of AKT activation, overexpression of ERG and AR in basal cells closely recapitulated the histological and molecular features of human prostate cancer, with loss of basal cells and expansion of malignant luminal cells expressing PSA and AMACR." (PMID 23852643, 2013). "Thus, Jiang and co-workers used immunohistochemistry with a triple-antibody cocktail (containing antibodies to AMACR, high molecule-weight 34βE12, and p63) to identify small, focal prostate carcinomas with high sensitivity and complete specificity." (PMID 22800084, 2012). "Previous studies have suggested that two basal cell markers may be stained together with AMACR in a triple-antibody cocktail, further improving the ability to recognise limited prostatic carcinoma foci." (PMID 22800084, 2012). "Furthermore, epidemiologic, genetic and laboratory studies have pointed to the importance of AMACR in prostate cancer." (PMID 25586028, 2012). "Indeed, β-oxidation pathway is suggested to be up-regulated in prostate cancer and α-methylacyl-CoA racemase (AMACR), an enzyme involved in branched chain fatty acid β-oxidation, is already being explored as a diagnostic marker of prostate cancer." (PMID 21787388, 2011). "In addition, the sensitivity and specificity of HMWCK as well as AMACR for the detection of prostate cancer and benign prostatic tissue were also evaluated." (PMID 21176184, 2010). "In conclusion, we have provided evidence that AMACR is a potent immunogenic antigen for prostate cancer and AMACR-derived peptides might serve as a cancer vaccine for HLA-A24-positive prostate cancer patients." (PMID 20003233, 2009). "Our study demonstrates that AMACR could become a target antigen for prostate cancer immunotherapy, and that the AMACR-derived peptides might be good peptide vaccine candidates for HLA-A24-positive AMACR-expressing cancer patients." (PMID 20003233, 2009). "Initial studies reported that AMACR was overexpressed in 94-100% of prostate cancers though recent studies have demonstrated a slightly lower expression rate in the range of 80-90% for prostate cancer." (PMID 20003233, 2009). "The recent finding of molecular alterations in AAH including immunoreactivity for AMACR, a marker linked to prostate adenocarcinoma, suggests that at least a subset of AAH cases might be related to prostate carcinoma of the transition zone." (PMID 18700013, 2008).
prostate carcinoma (continued). "Genes over-expressed in prostate cancer include AMACR, HPN, RDH11, and TMPRSS2." (PMID 16638148, 2006). "Interestingly, AMACR-negative expression in prostate cancer was associated with a heterogeneous PTEN loss, while its positive expression was linked to PTEN homogeneous loss." (PMID 37185705, 2023). "However, the mechanism underlying the correlation between AMACR and prostate cancer has not been clarified yet." (PMID 35627227, 2022). "In addition, AMACR has been found to be overexpressed in prostate cancer." (PMID 32760737, 2020). "Indeed, numerous studies have shown elevated AMACR levels as a reliable prostate cancer marker." (PMID 32674458, 2020). "Furthermore, AMACR polymorphism did not modify the associations between dietary red meat or dairy intake on prostate cancer in the population-based case-control study in the state of Washington." (PMID 31436750, 2020). "An enzyme (AMACR) confined to peroxisomes, involved in fat metabolism and also function as a growth promoter but does not depend on androgens in case of prostate cancer experimentally also observed to depict overexpressed production in prostate cancer assisting diagnosis." (PMID 32055737, 2020). "In addition, the function of AMACR in prostate cancer is very important." (PMID 32760737, 2020). "In addition to prostate cancer, AMACR positivity has been demonstrated in 90% cases of HGPIN suggesting that the possibility of HGPIN must be carefully excluded by morphology and the use of basal cell markers, before AMACR positivity is used to establish the diagnosis of adenocarcinoma." (PMID 21176184, 2010). "To confirm that CTLs induced with AMACR peptides could exert cytotoxicity against AMACR-expressing prostate cancer cell lines in an HLA-A*2402-restricted manner, we examined their cytotoxic activity against prostate cancer cell lines that express endogenous AMACR by 51Cr-release assay." (PMID 20003233, 2009). "α-methyl acyl CoA racemase (AMACR) is also an important enzyme involved in FAO and is specifically overexpressed in colorectal cancer, liver cancer, and prostate cancer." (PMID 41421797, 2025). "The canonical prostate adenocarcinoma markers AMACR (p504s) and KLK3 (PSA) were robustly expressed in the castration‐resistant prostate cancer (CRPC) epithelia." (PMID 38483933, 2024). "As expected, KLK3 Ct values strongly correlated with Ct values of other genes which have been reported to play a role in prostate cancer (i.e., PCA3, AMACR, TRPM8, MSMB and PSGR)." (PMID 32630458, 2020). "Moreover, the findings that AMACR expression was elevated not only in prostate cancer but also in colon, gastric, breast, renal, and hepatocellular carcinoma suggest that peroxisomal branched chain fatty acid metabolism may be associated with a broader range of tumors in addition to prostate cancer." (PMID 32674458, 2020). "Alpha-Methylacyl-CoA racemase (AMACR), which was initially discovered as a prostate cancer marker, is critical for the chiral inversion mechanism of branched-chain fatty acids." (PMID 33154941, 2020). "The established methods for detecting prostate cancer (CaP) are based on tests using PSA (blood), PCA3 (urine), and AMACR (tissue) as biomarkers in patient samples." (PMID 25889691, 2015). "Alpha-methylacyl-CoA racemase (AMACR), pristanoyl-CoA oxidase (ACOX-3) and D-bifunctional protein (DBP), are also important fatty acid oxidation-related proteins in prostate cancer, and we also included them in our analysis." (PMID 24886074, 2014). "In human clinical prostate cancer specimens, TSPY was predominantly detected in the epithelial tumor cells, which were also positive for the tumor biomarker, alpha-methylacyl-CoA racemase (AMACR)." (PMID 24528896, 2014). "AMACR is critical in prostate cancer cell progression; the downregulation of AMACR expression hampers the proliferation of the LAPC-4 androgen-responsive prostate cancer cells." (PMID 24383053, 2013).